SCN8A (sodium voltage-gated channel alpha subunit 8)
Diseases named in the same sentence as SCN8A in open-access papers (continued):
Sharing a sentence is not in itself a finding about the gene and the disease.
Photophobia (1 paper, 2024). Excessive sensitivity to light with the sensation of discomfort or pain in the eyes due to exposure to bright light. "It worth noting that, Scn8a exhibit a pronounced gene expression change following photophobia and SFKs antagonism (> 10)." (PMID 39390364, 2024).
psoriasis (1 paper, 2025). An autoimmune condition characterized by red, well-delineated plaques with silvery scales that are usually on the extensor surfaces and scalp. "According to GTEX, rs115692430 correlates with SCN8A expression; however, it does not in tissues relevant to psoriasis." (PMID 41153404, 2025).
Sleep disturbance (1 paper, 2024). An abnormal pattern in the quality, quantity, or characteristics of sleep. "Our study showed that the majority of patients with SCN8A‐related disorders experience sleep disturbances, mainly consisting of difficulties in initiating and maintaining sleep." (PMID 39361253, 2024). "More than 80% of patients with SCN8A‐related disorders presented with sleep disturbances, primarily consisting of sleep instability with difficulty of initiating and maintaining sleep." (PMID 39361253, 2024).
West syndrome (1 paper, 2023). "Of nine SCN8A variant patients, one was diagnosed with West syndrome, one with Lennox–Gastaut syndrome (LGS), one with benign familial infantile epilepsy (BFIE), and six with non-specific EE." (PMID 38174099, 2023).
cancer (24 papers, 2014 to 2024). A tumor composed of atypical neoplastic, often pleomorphic cells that invade other tissues. "The inhibition of SCN8A in primary cultured CC cells using Cn2 toxin and tetrodotoxin significantly reduces the invasiveness of these cancer cells." (PMID 37408210, 2023). "As previously indicated, the three main NaVα-encoding genes found to be upregulated in cancers are SCN5A, SCN8A, and SCN9A, which encode NaV1.5, NaV1.6, and NaV1.7, respectively." (PMID 33817575, 2021). "In conclusion, this study shows that SCN8A gene expression is upregulated in human cervical tissue only when cancer has been established." (PMID 30158710, 2018). "Therefore, further studies are needed to fully understand the function of SCN8A across different types of cancer." (PMID 33817575, 2021). "HeLa (HPV18+), SiHa, and Caski (both HPV16+) cells show the overexpression of SCN8A, and its induced expression increases the activity of the matrix metalloproteinase MMP-2, which leads to cancer invasion and progression." (PMID 37408210, 2023).
movement disorder (16 papers, 2013 to 2026). Neurological conditions resulting in abnormal voluntary or involuntary movement, which may impact the speed, fluency, quality and ease of movement. "Myoclonus is the main type of movement disorder associated with CACNA1A (approximately 82.8%), KCNA2 (75%), SCN1A (approximately 61.5%), and SCN8A (60%) mutations." (PMID 40217411, 2025). "Movement disorders are commonly observed in SCN8A-related phenotypes, and the zebrafish model has demonstrated that SCN8A expression is critical for normal motility during early embryonic development." (PMID 41007641, 2025).
neurodevelopmental disorder (13 papers, 2017 to 2026). A behavioral and cognitive disorder with onset during the developmental period that involves impaired or aberrant development of intellectual, motor, or social functions. "SCN8A, a sodium voltage-gated channel gene essential for neuronal excitability, has been associated with neurodevelopmental disorders including ASD." (PMID 40470234, 2025). "Pathogenic variants in SCN8A, which encodes NaV1.6, have emerged as important causes of neurodevelopmental disorders, with typical onset during infancy." (PMID 38771640, 2024). "Since the development of next generation sequencing, many pathogenic variants of SCN8A have been identified in patients with a spectrum of neurodevelopmental disorders, and some genotype-phenotype correlations have emerged." (PMID 35557557, 2022). "Interestingly, dominant variants in SCN8A are often implicated with more global neurodevelopmental disorders." (PMID 37328295, 2023). "In a recent survey of autosomal dominant de novo monogenic rare neurodevelopmental disorders, SCN8A-RD had an estimated prevalence of 2.96/100,000 individuals (95% CI 2.63–3.24/100,000 individuals)." (PMID 40830973, 2025). "Given that many comorbidities are not unique to SCN8A-RD patients, a third priority is to collect data across channelopathies and DEEs to increase our understanding of comorbidities along the spectrum of neurodevelopmental disorders." (PMID 40830973, 2025).
tumor (13 papers, 2015 to 2025). "Among patient tumor samples, lower SCN8A expression was associated with improved overall survival (OS) (median 111 vs. 52 months; HR 2.04 95% CI: 1.21–3.44; p = 0.007), while lower SCN1B expression was associated with poorer OS (median 45 vs. 56 months; HR 0.69 95% CI 0.54–0.87; p = 0.002)." (PMID 34771603, 2021). "Inhibition of SCN8A significantly reduced the invasive potential of cancerous cells, pointing to the key role of VGSCs in tumor progression." (PMID 40361464, 2025). "Results also reveal a relationship between SCN8A expression, gender, grade of CRCa, tumor location, and histopathological classification." (PMID 33817575, 2021). "SCN8A mRNA levels, analyzed by real-time qPCR, were significantly lower in tumor tissues and in patients younger than 45 years." (PMID 33817575, 2021). "First, qPCR experiments clearly shown that CeCa cell lines express similar levels of NaV1.6 channel messenger (SCN8A gene) to those found in some CeCa tumor biopsies." (PMID 30158710, 2018). "Based on the cell line data, we focused on the relationship between SCN8A and SCN1B tumor expression and overall survival from EOC after optimal cytoreductive surgery followed by platinum-based chemotherapy." (PMID 34771603, 2021). "Additionally, SCN8A overexpression in HeLa, SiHa, and CaSki cell lines increased MMP-2 activity, which promoted tumor invasion and progression." (PMID 40361464, 2025). "The contrasting prognostic significance of SCN8A and SCN1B tumor expression raised the possibility that VGSC blockade could be either helpful or harmful EOC." (PMID 34771603, 2021). "A significantly lower expression of SCN8A was found in colorectal tumor tissues compared to paired tumor-surrounding non-cancerous tissues, and in patients below the age of 45 compared to older patients." (PMID 26283962, 2015).
neurological disorders (11 papers, 2013 to 2025). "This rapid progress indicates that mutations of SCN8A are a previously unrecognized cause of these and possibly other neurological disorders." (PMID 24194747, 2013). "This narrative review summarizes some of the most recent therapeutic approaches approved or under investigation for the treatment of SCN1A-, SCN2A- and SCN8A-related neurologic disorders." (PMID 41515912, 2025).
infection (4 papers, 2015 to 2023). The state of being infected such as from the introduction of a foreign agent such as serum, vaccine, antigenic substance or organism. "Like SLC9A3R2, SCN8A down and up-regulation at 3 dpi and the two later time points respectively also indicated sodium balance regulation during infection." (PMID 25903558, 2015).
neurodegenerative disease (3 papers, 2019 to 2023). A disorder of the central nervous system characterized by gradual and progressive loss of neural tissue and neurologic function. "Interestingly, all known SCN8A-associated human neurodegenerative diseases are caused by dominant acting variants (OMIM 600702)." (PMID 31083464, 2019). "Conversely, VGSCs seem to have a modulatory role in the most common neurodegenerative diseases such as Alzheimer’s, where SCN8A expression has been shown to be negatively correlated with disease severity." (PMID 37240836, 2023).
psychiatric disorder (2 papers, 2013 to 2019). A disorder characterized by behavioral and/or psychological abnormalities, often accompanied by physical symptoms. "Mutation of SCN8A, which encodes Nav1.6, is also involved in the susceptibility of suicidal behavior among psychiatric disorder patients." (PMID 31920555, 2019).
SCN8A also shares sentences with these, for which no sentence is quoted: cerebellar ataxia (8 papers); trigeminal neuralgia (8); autism spectrum disorder (7); neuropathic pain (7); bipolar disorder (4); infantile epileptic encephalopathy (4); neuropathy (4); complex regional pain syndrome (3); long QT-Syndrome (3); microcephaly (3); multiple sclerosis (3); Parkinson’s (3); Angelman syndrome (2); Arrhythmia (2); brain disorder (2); breast carcinoma (2); diabetic neuropathy (2); Ewing sarcoma (2); generalized tonic-clonic seizures (2); genetic generalized epilepsy (2); injury (2); lymph node metastasis (2); Neurodevelopmental delay (2); Pain (2); respiratory failure (2); schizophrenia (2); -dependent (1); Acute encephalopathy (1); Atrophy (1); behavioral disturbances (1).
A further 51 diseases each share a sentence with SCN8A in 1 paper.